SNORD115-37 (small nucleolar RNA, C/D box 115-37)
Synonyms: HBII-52-37
Gene: Small nucleolar RNA gene on chromosome 15 (25,237,986 to 25,238,067, forward strand). Ensembl gene ENSG00000200638.
Gene Ontology:
Biological process: RNA processing
Cellular component: nucleolus
Homologues: Orthologues: chimpanzee SNORD115 (100% identical). Paralogues in human: SNORD115-20 (90% identical), SNORD115-27 (90% identical), SNORD115-12 (89% identical), SNORD115-9 (89% identical), SNORD115-1 (88% identical), SNORD115-10 (88% identical), SNORD115-11 (88% identical), SNORD115-13 (88% identical), SNORD115-17 (88% identical), SNORD115-18 (88% identical), SNORD115-19 (88% identical), SNORD115-29 (88% identical), and 37 more.